TNF (tumor necrosis factor)
Diseases named in the same sentence as TNF in open-access papers (continued):
Sharing a sentence is not in itself a finding about the gene and the disease.
tumor (continued). "Moreover, upon antigenic activation in vitro, PB CAR-T cells released lower levels of IFN-γ, IL-6, IL-10, TNF-α, CCL2, CXCL10, and GM-CSF than Lenti CAR-T cells, but demonstrated a robust release of IL-9, indicative of a distinct anti-tumor response pathway." (PMID 37228617, 2023). "Indeed, tumor growth was found to be accelerated in mice with T‐cell‐specific deletion of Cbx4 and the tumor‐infiltrating T cells from these mice were defective in IFN‐γ and TNF‐α production." (PMID 37691307, 2023). "However, while among the anti-tumoral cytokines, TNF-α and IL-6 levels resulted both increased, IFN-γ level dropped in tumor mass of β3-AR antagonist-treated mice." (PMID 36854895, 2023). "An increase in ID8 tumor-specific recall responses was also seen from CD4+ T cells isolated from the peritoneal lavage fluid of OrfV-treated mice but not control animals, based on the increased expression of IFN-γ and IFN-γ and TNF-α." (PMID 38075247, 2023). "In addition, miR-296 has been shown to block the expressions of several pro-angiogenic signals involved in tumor growth, such as VEGF, PDGF and TNF." (PMID 37108432, 2023). "CD8+TILs can exert anti-tumor functions through several pathways such as the release of GZMA and GZMB, Fas-Fas ligand pathway-mediated apoptosis, and secretion of inflammatory cytokines like IFN-γ and TNF-α." (PMID 37781365, 2023). "Furthermore, at 21 months tumor incidence was positively correlated with blood MCP-1 (rho = 0.1682, p = 0.0341) and TNFα (rho = 0.2388, p = 0.0021)." (PMID 38125727, 2023). "Tumor necrosis factor (TNF) matters in immune regulation and controlling tumor growth." (PMID 37153540, 2023). "Moreover, upregulation of CD36 in CD8+ T cells leads to excessive lipid accumulation, which impairs secretion of anti-tumor factors such as IFN-γ and TNF-α, ultimately suppressing their anti-tumor efficacy." (PMID 37700339, 2023). "For example, TNF, IL-6, and IFN- γ upregulate PD-L1 expression in tumor cells." (PMID 36941614, 2023). "Additionally, the knockdown of IGSF6 in M1 macrophages decreased the production of IL-12 and TNFα by M1 macrophages and accelerated the LUAD progression, indicating that IGSF6 is involved in the anti-tumor activity of M1 macrophages." (PMID 38037023, 2023). "We noted that the neutrophils from tumors generated in qMCP−/−; Ntv-a mice appeared to be enriched in interactions with many tumor clusters (T0, and T2 to T5) through secretion of tumor necrosis factor α (TNF-α) and signaling via TNF-α receptor-I (TNFR-I: p55) and DAG1 on tumor cells." (PMID 37012245, 2023). "Furthermore, both CD4+ and CD8+ T cells with anti-tumour functionality (particularly IFN-γ and TNF co-production) are enriched within the PD-1+ fraction of MC38 TILs." (PMID 37153625, 2023). "Metabolites of gut microbiota (e.g., butyric acid, pentanoate, and butyrate) also induced Treg cell differentiation, increased the secretion of anti-tumor cytokines (e.g., IFN-γ and TNF-α) by CD8+ T cells, and enhanced the anti-tumor responses of antigen-specific CTLs and CAR-T cells." (PMID 37131214, 2023). "Importantly, we found that 80% of the analysed genes were strongly induced by TGF-β in tumour derived KPC cells, whereas TNF-α significantly upregulated only 20% of these genes." (PMID 37823551, 2023). "This study suggested that high expression of Tim-3 may inhibit the secretion of TNF-α and IFN-γ by immune cells, leading to tumor progression." (PMID 36865498, 2023). "Meanwhile, the tumor-triggered glycolytic switch in monocytes has been found to induce the activation of hypoxia-inducible factor (HIF)1α and the production of tumor necrosis factor (TNF)-α, interleukin (IL)-10, and IL-1β, which in turn synergistically upregulates the CAXII expression in monocytes." (PMID 37006233, 2023).
tumor (continued). "Following in vivo interaction of CAR T- and tumor cells, CAR T-cells liberate inflammatory cytokines (e.g., TNF-α and IFN-γ), leading to the hyperactivation of macrophages and the secretion of large amounts of IL-6 and IL-1β, which can be effectively abolished by the use of corticosteroids." (PMID 36830750, 2023). "The expression of TNF, an endogenous ligand of TNFR2 with the capacity to up-regulate TNFR2 expression by Tregs, in tumor tissue could be markedly upregulated after ICIs treatment." (PMID 36865537, 2023). "In fact, HFD-induced dysbiosis favors PMN development in the lung through the activation of nuclear factor-κB (NF-κB) signaling and the release of cytokines such as tumor necrosis factor-α (TNF-α) and C-C chemokine ligand 2 (CCL2) by M1-macrophages, which are able to promote tumor progression." (PMID 36674986, 2023). "Furthermore, NEAT1 or LDHA knockdown promoted the secretion of CD8+ T-lymphocyte factors, including TNF-α and IFN-γ, enhancing the anti-tumor effects." (PMID 36831498, 2023). "Secondly, we quantified release of cytokines (i.e., IFNγ, IL-10, IL-2, IL-6, TNFα, GM-CSF, IL-12p70, IL-1b and IL-8) and granzyme B by using the MSD platform in supernatants collected from the TDCC assay with the tumor cell lines SK-CO-1, MKN-45 and H2122 after 48 h." (PMID 38087365, 2023). "On the CT26 and B16F10 tumor models, both local and systemic, CMP enhanced the expression of interferon‐β (IFN‐β), tumor necrosis factor‐α (TNF‐α), and CXCchemokineligand‐10 (CXCL10) proinflammatory cytokines, and promoted tumor invasion of CD8+ T cells, thus showing a good therapeutic effect." (PMID 37933288, 2023). "Furthermore, melatonin reduces the secretion of the pro-inflammatory cytokines TNF-α and IL-8 when cocultured with MCF-7 cells, which are closely related to tumor development and reinforce the potential of melatonin as a therapeutic strategy for cancer." (PMID 37569777, 2023). "As a result, STING agonist administration enhances the expression of IFN-β and other proinflammatory cytokines (e.g., IL-6 and TNF-α) or chemokines (e.g., CCL2/3/4/5 and CXCL9/10), the maturation and functions of DCs, and the expansion of tumor-infiltrating CD8+ T cells." (PMID 38008741, 2023). "Besides, TNFα-NF-κB and IL-6-STAT3 signaling pathways are collaboratively involved in promoting endothelial-mesenchymal transition and tumor progression." (PMID 36978108, 2023). "For example, the negative correlation between patient outcome and level of tumor-associated macrophages (TAM) is reliant upon TAM expression of PDGF, TGF-β, EGF, IL-1, IL-6 and TNF-α, which generates a favorable environment for tumor growth." (PMID 37568595, 2023). "Interestingly, in contradiction to their dysfunctional phenotype, these cells were capable of rapid IFN-γ and TNF production ex vivo, while CD8+ TILs with anti-tumour functionality ex vivo (IFN-γ and TNF co-production) were predominately PD-1+." (PMID 37153625, 2023). "These infiltrated immune cells and solid tumor cells release tumor-progressing cytokines (IL-6, TNF-α, TGF-β), chemokines (CCL2, CCL5, CCL18, CXCL8, CXCL12), and growth factors (EGF, PGF, IGF-1, IGF-2, PDGF) that promote tumor microenvironment immunosuppressive." (PMID 37371075, 2023). "Lipopolysaccharide and pro-inflammatory cytokines, such as interferon-γ (IFN-γ), can trigger M1 macrophages to secrete tumor necrosis factor-α (TNF-α), pro-inflammatory cytokines, including interleukin-1 (IL-1), IL-6, IL-8, and IL-12, and promote anti-tumor immune response." (PMID 37313405, 2023). "By contrast, other studies speculate that MCs may promote inflammation, inhibition of tumor cell growth, and tumor cell apoptosis by releasing mediators such as IL-1, IL-4, IL-6, IL-8, Mcpt3, Mcpt4, INF-y, TNF-α, TGF-β, LTB4, and chymase." (PMID 37686555, 2023). "Moreover, the administration of 131I upregulates the secretion of tumor necrosis factor-α (TNF-α) and its receptors TNFR1 and TNFR2 to initiate anti-tumor effects." (PMID 36776316, 2023).
tumor (continued). "In addition, serum levels of TNF-α, IL-6 and VEGF also showed statistical difference in all above different tumor-related factors (all P < 0.001)." (PMID 37430251, 2023). "For example, NK cells can be recruited by C-X-C motif chemokine ligand 9 (CXCL9), produced in activated CD103+DCs (dendritic cells), into the tumor microenvironment to express granzyme B, interferon-gamma (IFN-γ), and tumor necrosis factor-alpha (TNF-α) to kill HCC cells." (PMID 37239062, 2023). "Kupffer cells (KCs) may increase production of NO and TNF-α and IFN-γ to induce apoptosis of tumor, showing the effect of anti-tumor." (PMID 38090482, 2023). "Macrophages may internalize and secrete TNF- α, NO, IFN-γ, IL-2, IL-6, IL-8, IL-12 and IL-18, so as to play an anti-inflammatory and even anti-tumor role." (PMID 35299759, 2022). "Moreover, H. pylori has the ability to secrete a protein meant to stimulate TNF-α production, the TNF-α-inducing protein (Tipα), which will enable H. pylori to act as a tumor promoter." (PMID 35884067, 2022). "Unfortunately, despite the impressive anti-cancer effects observed in mice, studies performed in cancer patients in the late 1980s showed that TNF, upon systemic administration, can induce toxic effects and no, or very modest, anti-tumor responses." (PMID 35890309, 2022). "The response of tumors to TNF-α in vivo is also very different, which is not parallel to the sensitivity of tumor cell lines to TNF-α in vitro." (PMID 36035842, 2022). "Importantly, the number of TNFα+ and TNFαIFNγ+ CD4+ T cells significantly correlated with lower tumor growth rates, while the CD8 T cells showed a less drastic effect." (PMID 36419897, 2022). "Interaction network results revealed that BAK1, NLRP1, CHMP7, and RIPK1 genes could interact with immune factors, including TNF-α, suggesting their influence on the immune microenvironment of the HNSCC tumor." (PMID 36246601, 2022). "Overall, these data show that IFNγ and TNFα secreted from T cells during TDCC can induce TYMP gene transcription followed by TP protein synthesis in MKN45, which efficiently converts capecitabine to 5′-FU at the tumour site." (PMID 36071036, 2022). "CD8+ T cells co-cultured with NDV-preinfected tumor cells in the presence of SEB showed significantly greater proliferation and IFN-γ production than those cultured with untreated tumor cells; CD4+ T cells similarly increased their TNF and IFN-γ production." (PMID 36418317, 2022). "TNF-α and IFN-γ are powerful in monitoring tumor proliferation and trigger cell death." (PMID 36443314, 2022). "Salmonella LPS could induce tumor-specific CD8+ T cell responses and the elevation of tumor necrosis factor-α (TNFα) in both TME and peripheral blood." (PMID 36276157, 2022). "The chimeric-antigen-receptor-tumor-induced-vector (CARTIV) platform, based on promoter-responsive elements (PREs) of gamma interferon (IFN-γ), tumor necrosis factor α (TNF-α), and hypoxia, exhibits synergistic activity in cell lines and effective activation in T cells without loss of safety." (PMID 36291802, 2022). "Besides, the pathological activities of TNF-α are important in early events of tumors, as it regulates a cascade of cytokines, chemokines, adhesions, matrix metalloproteinases, and pro-angiogenic activities and thus may be involved in the mechanism by which inflammation acts as a tumor promoter." (PMID 34251535, 2022). "Together these data demonstrate that hypersecretion of TNF in the absence of NKG7 compensates for inefficient synapse-mediated cytotoxicity to control MC38-OVA tumor growth." (PMID 35874669, 2022). "Searching for lipolysis activation pathways that are independent of the β-adrenergic–cAMP–protein kinase A (PKA) signaling cascade, we found increased TNFα and iNos mRNA expression levels in iWAT of LLC-bearing IL-4-ra-KO animals compared with tumor-bearing WT mice." (PMID 35210363, 2022).
tumor (continued). "Notably, chromogranin A, a neurosecretory glycoprotein capable of inhibiting the vascular leakage induced by TNF, can also inhibit the synergism between NGR-TNF and chemotherapeutic drugs in tumor-bearing mice." (PMID 35890309, 2022). "Natural killer (NK) cells are specialized immune effector cells that are able to kill tumor cells and are the main source of cytokines and chemokines such as interferon (IFN)-γ and TNF-α, which regulate the function of lymphocytes and enhance the antigen-specific T-cell response." (PMID 36591235, 2022). "Ruxo relies on T cells and host TNF signaling but not direct killing of tumor cells to exert its selective efficacy." (PMID 36008408, 2022). "The presence of apoptotic tumour cell-CM had no impact on the inhibitory effect of neutrophils on macrophage TNFα secretion." (PMID 35121727, 2022). "At present, some researchers have confirmed that after PC saponin administration, serum IL-6 and TNF-α levels, expression of VEGF and CD31 in liver tissues, and CXCR4, CXCL12, MMP-9 and MMP-2 proteins in spleen tumor tissues of colon cancer mice were significantly reduced." (PMID 35814470, 2022). "Previously, owing to the extensive non-specific effects of TNF, this signaling pathway was abandoned as the main treatment option during clinical anti-tumor therapy." (PMID 35494080, 2022). "It has also been reported that immunosuppressive therapy, such as PSL or anti-TNF-α agents of irAE, does not affect the anti-tumor effects of ICI treatment." (PMID 35482642, 2022). "Additionally, MTORC1 signaling, TNF-alpha signaling and MYC-targets were overexpressed compared to the tumor tissue in vivo." (PMID 35646693, 2022). "Similarly, increased monocytes have been indicative of increased tumor cell growth and angiogenesis given their ability to produce inflammatory mediators such as vascular endothelial growth factor (VEGF) and TNF‐α." (PMID 36325601, 2022). "Six pathways were specifically active in tumors compared to PBMC, including known inflammatory signals MIF, TNF, and IL16, suggesting that these pathways might critically contribute to tumor progression." (PMID 35812372, 2022). "Immunofluorescence or fluorescence-activated cell sorting showed that CD8+ T cell infiltration after treatment with BJJP and BJJP treatment also promoted the effector function of CD8+ T cells by significantly increasing the expression of TNF-α and IFN-γ in tumor-infiltrating CD8+ T cells." (PMID 36212483, 2022). "Furthermore, TNF-α and TGF-β released from macrophages interact during EMT, jointly regulating tumor invasion and metastasis." (PMID 35965509, 2022). "CK2 inhibitors can reduce the release of TNF, IL-6, and VEGF cytokine in cancer cells.CK2 inhibitors can suppress the production of tumor-derived factors (TDF) to modulate immune cells development and promote tumor regression." (PMID 36530985, 2022). "However, some studies have found that neutrophils secrete large numbers of pro-inflammatory factors, including TNF-α, MIP-α, H2O2 and NO, which directly kill tumor cells." (PMID 35493517, 2022). "Twenty-five common tumor-specific intercellular communications were identified in more than four datasets, mainly involved in intercellular communication from other cells to Mono/Macro, including CCL3/4/5-CCR1/5 and TNF–TNFRSF1B signaling." (PMID 36230879, 2022). "With the aid of CpG, TAAs produced by PDT-induced tumor cell damage can enhance the presentation ability of DCs, which promotes the maturation of CD4+T cells and CD8+ T cells and the release of cytokines (including INF-γ, TNF-α)." (PMID 35832074, 2022). "To investigate the mechanisms by which tumors became absent, we investigated the expression of the tumor necrosis marker, TNFα, and the apoptosis markers, cleaved Caspase‐3 and PARP, in the xenografts from the GalNac‐siNC and GalNac‐siHK2 groups." (PMID 35603967, 2022).
tumor (continued). "As the immune system is activated, a series of representative cytokines interleukin-2 (IL-2), IL-10, IL-12, IL-1β, interferon γ (IFN-γ), tumor necrosis factor α (TNF-α) of T cells that regulate the immune response in the serum significantly increased, improved the anti-tumor immunity." (PMID 35651605, 2022). "TNF-α, IL-10, and IL-1β mimicked the effects of TSN in inducing the upregulation of CA12 expression in monocytes, and consistently, anti–TNF-α, anti–IL-10, and anti–IL-1β antibodies attenuated the induction of CA12 in tumor-exposed monocytes." (PMID 35362480, 2022). "Besides, the expression of IL-6 and TNF-α were upregulated while the expression of IL-10, CCL22, Arg-1 and CD206 were downregulated in the tumor tissues from ACEA-treated group." (PMID 35641479, 2022). "Extensive research has shown that intestinal microbes stimulate the expression of chemokines such as TNF- α, IL-6, IL-10, and IL-1β or activate cytotoxic lymphocytes, such as CD4+ and CD8+ T cells or NK and NKT cells, in both peripheral blood and tumor to limit tumor growth." (PMID 36232344, 2022). "Furthermore, galectin-9 on both γδ T cells and pancreatic tumor cells has been shown to bind dectin-1 on tumor-infiltrating macrophages, leading to M2 macrophage polarization and subsequent downregulation of IFN-γ and TNF-α production by γδ T cells." (PMID 35880177, 2022). "The absence of chemerin enabled an increase in TNF, a cytokine that despite its name, often contributes to tumor progression by contributing to a growth-conducive environment." (PMID 36289872, 2022). "This tri‐modality therapy resulted in an increase in the number of tumor‐infiltrating CD8+ T cells, activation of NK cells, enhancement in secretion of cytokines such as IL‐12 and TNF‐α, a tumor inhibition rate of 84.2%, and effective restraint of the lung metastasis." (PMID 35652198, 2022). "Although the numbers of total CD8+ T cells remained unchanged, the transcription levels of cytokines IFNγ and TNFα were notably increased in the pyrimethamine group, indicating that CD8+ T cells were activated in the tumor microenvironment after pyrimethamine treatment." (PMID 35262820, 2022). "It blocks NF-κB in the inflammatory tumor microenvironment which subsequently inihibits pro-inflammatory mediators like tumour necrosis factor α (TNF-α) and interleukin (ILs) and enzymes (COX1/2), resulting in the inhibition of tumor progression and metastasis." (PMID 36307808, 2022). "NK cells kill target cells and restrain primary tumor progression through various pathways including: antibody-dependent cell-mediated cytotoxicity (ADCC), Fas/FasL pathway, perforin/granzyme pathway, and release of cytokines such as TNF." (PMID 36405712, 2022). "PHA treatment induced the tumor slices from all 8 patients to produce significant levels of TNF-α and IFN-γ compared with no treatment." (PMID 35463322, 2022). "We observed that, in vivo, intratumoral administration of AZ505 in the absence of TNF supplementation also induced apoptotic cell death and reduced tumor size." (PMID 35022391, 2022). "Meanwhile, the ratios of CD8+IFN-γ+ T, CD8+ IL-2+ T, CD8+TNF-α+ T, and CD8+Granzyme B+ T cells in the splenocytes of Cal/ICG@MPs with 808 nm laser irradiation-treated mice was significantly increased after tumor antigen restimulation." (PMID 35589680, 2022). "Flow cytometry analysis of resected 4T1 tumors collected from a separate experiment showed that the combination treatment resulted in increased expression of IFNγ, TNFα, and granzyme B in intratumoral CD8+ T and NK cells, as well as an overall increase in tumor-infiltrating CD8+ T cells." (PMID 35840558, 2022). "The human immunodeficiency virus type I enhancer binding protein (HIVEP) family, which contains zinc finger and acid‐rich (ZAS) domains, has been demonstrated to be implicated in vital biological processes, such as cell survival, tumor necrosis factor (TNF) signaling, and tumor formation." (PMID 35535739, 2022).